SYNE1 (spectrin repeat containing nuclear envelope protein 1)
Diseases named in the same sentence as SYNE1 in open-access papers (continued):
Sharing a sentence is not in itself a finding about the gene and the disease.
teratoma (1 paper, 2022). A non-seminomatous germ cell tumor characterized by the presence of various tissues which correspond to the different germinal layers (endoderm, mesoderm, and ectoderm). "In our study, CARD11(caspase recruitment domain family member 11) (mutated in 18% intracranial teratomas), IRS1(insulin receptor substrate 1) (18%), PSMD11(16%), RELN(16%), RRAS2(16%), SMC1A(16%), SYNE1(16%) and ZFHX3(16%) were the tumor-related genes with the highest mutation rates in our cohort." (PMID 36457486, 2022).
uterine disorder (1 paper, 2024). A non-neoplastic or neoplastic disorder that affects the uterine corpus or the cervix. "The uterine disorders cluster (two) was significantly associated with six loci, WNT4, GREB1, BSN, SYNE1, GDAP1, and ASTN2." (PMID 39315247, 2024).
cancer (66 papers, 2003 to 2026). A tumor composed of atypical neoplastic, often pleomorphic cells that invade other tissues. "In addition, a study of 3,000 cancer genomes across nine cancer types identified mutations in the SYNE-1 gene encoding nesprin-1 as “drivers” in the development of cancer." (PMID 35663386, 2022). "Similar overall frequencies were observed comparing PR-low to PR-high cancers with the exception of SYNE1 mutations (27% versus 0%, p = 0.008; two-tailed test), although similarly this difference was not significant after multiple testing correction (p = 0.109; Benjamini Hochberg correction)." (PMID 35768582, 2022). "The rs9479297 genotypes have never been referred to as a predictor of disease occurrence or clinical prognosis in any other disease to date, albeit other genetic polymorphisms within SYNE1 gene have been implicated in numerous cancer types, other than HCC or TCC." (PMID 34944636, 2021). "SYNE1 gene mutations cause muscular dystrophy, cerebellar ataxia, arthritis, and cancer." (PMID 32670437, 2020). "Collectively, SYNE1 may be a candidate cancer mutated gene in COAD." (PMID 26352260, 2015). "Among cancer-related genes, CARD11(18%) and IRS1(18%) were the most common somatic mutated genes, followed by PSMD11, RELN, RRAS2, SMC1A, SYNE1 and ZFHX3, and the mutation rates of the latter six genes were all 14%." (PMID 36457486, 2022). "Our present results are consistent with most of the published literature, showing that lower SYNE1 expression is correlated with more aggressive cancer phenotypes." (PMID 34944636, 2021). "Numerous reports indicate that nesprin-1 is downregulated in oncological diseases, while mutations in SYNE1 have been identified in different types of human cancers." (PMID 33036298, 2020). "Further studies with SYNE1 protein expression and lncRNA interactions will throw more light into its role in cancer development and progression in all cancer types." (PMID 30809433, 2019). "Apart from SYNE1 and PKHD1 genes which were found to be maximally mutated to 22 other genes were identified as cancer driver genes which harbor 39 variants." (PMID 28324520, 2015). "All these results implied that ZNF831 and SYNE1 may be promising candidates for tumor antigen based cancer vaccine development in HCC." (PMID 40948427, 2025). "Since nesprin proteins regulate nuclear morphology and cell mobility, SYNE1 downregulation in cancer may increase nuclear malleability so that cells can migrate through narrow tissue spaces to invade neighboring tissues." (PMID 38742190, 2024). "SYNE1 has been shown to be downregulated in various human cancers." (PMID 28427185, 2017).
cancer (continued). "In addition, SYNE1 is one of the largest genes in the human genome and its function appears unrelated to hematopoiesis and cancer." (PMID 27590521, 2016). "The other frequently mutated genes, such as SYNE1, MUC16, etc. have been found to be mutated in other cancer types and may be novel candidate driver mutations in early stage of CRC tumorigenesis." (PMID 25923178, 2015). "Third, the two identified tumor antigen genes, ZNF831 and SYNE1, which have the potential to aid the development of cancer vaccines, should be viewed as hypothesis generating rather than conclusions, because the causal effects of the correlations cannot be determined in the current study." (PMID 40948427, 2025). "By quantifying cancer genome evolution using the gene gravity model, we identified six putative cancer genes (AHNAK, COL11A1, DDX3X, FAT4, STAG2, and SYNE1)." (PMID 26352260, 2015). "From the list of 20 FLAGS (FrequentLy mutAted GeneS) genes that are known to be frequently mutated in cancer but are unlikely to be pathogenic, TTN, AHNAK2, SYNE1, MUC16, and OBSCN were found among genes altered at ≥ 20% in mCLM." (PMID 38008721, 2023). "The relationship between ICAM1, TTN (Titin), and SYNE1 (Spectrin Repeat Containing Nuclear Envelope Protein 1) in cancer is not extensively studied, and their direct interplay in cancer is not well established." (PMID 37671167, 2023). "For the three cancers, SNVs were more likely to be detected in the high-OGT expression group than in the low-OTG expression group, and the top five genes with the highest frequency of SNV were MUC17, PIK3CA, SI, SYNE1, and PTEN." (PMID 35356257, 2022). "We also found that some of the identified genes, including TTN, MUC16, CSDM3, RYR2, USH2A, and SYNE1, are only altered in gynecological malignancies and not in other cancer types, highlighting their specific role in driving gynecological malignancies." (PMID 32626534, 2020). "Thus, in sum based on previous study, role of CSDM3, USH2A and SYNE1 is still not known in any cancer." (PMID 32626534, 2020). "SYNE1 (Nesprin 1), one of the PVT1 interacting genes, is a nuclear envelope protein, residing in outer nuclear membrane, and has been shown to play a role in cancers, the mode being speculated to be through DNA damage response pathway (Sur, Neumann & Noegel, 2014)." (PMID 30809433, 2019).
tumor (59 papers, 1990 to 2026). "Previous studies demonstrated an association between SYNE1 mutation, increased tumor mutation burden (TMB), and immunotherapy response." (PMID 37762518, 2023). "A study in renal cell carcinoma identified SYNE1 as a marker for high tumor mutation burden (TMB) and response to immune checkpoint inhibitors (ICI)." (PMID 37762518, 2023). "They showed that SYNE1 mutations correlate with immune system pathways and immune cell tumor infiltration." (PMID 33031058, 2020). "We also compared immune cell infiltration between those with SYNE1 mutation type (mt) and those with wild type (wt), and evaluated the utility of SYNE1 mutation as a ICB biomarker using the tumor immune dysfunction and exclusion (TIDE) algorithm." (PMID 33031058, 2020). "SYNE1 is associated with both an increased tumor mutation burden and overexpression of MS4A1." (PMID 37762518, 2023). "DelSIEVE identified many single point mutations on the branch leading to the two tumor subclones, including a reported CRC driver mutation in gene SYNE1, as well as a mutation related to DNA mismatch repair, in gene MLH3." (PMID 40855447, 2025). "Mutations in certain large genes, such as TTN, NEB, SYNE1, MUC16, and OBSCN, have previously been associated with tumor mutation burden (TMB)." (PMID 38473427, 2024). "Given the previous association of SYNE1 mutation with tumor mutation burden (TMB), we compared the TMB status of SYNE1 wild-type (WT) to SYNE1 mutated patients." (PMID 37762518, 2023). "It is notable that HLALOH occurred in the samples with recurrent mutations of S-C clonal pattern including KRAS, SYNE1, FBXL2, DNAH11 and CACNA1H, indicating this mutational clonal patter is facilitating tumor cell to escape immune monitor." (PMID 34453042, 2021). "SYNE1 and FOXE1 are two genes that have been recently linked to tumor growth, especially in gastrointestinal cancer." (PMID 33946400, 2021). "Especially, some tumor suppressor genes (TSGs) including DLC1 and SYNE1, which have been found to be downregulated in our GII tumor samples compared to GI samples, were predominantly mutated in GII-like TCGA patients." (PMID 34001209, 2021). "HNF1A, ESR1, and FLT4 were mutated significantly more frequently in tumor tissue samples obtained from patients with stage III BC, while SYNE1, PER1, and LRP1B were mutated significantly more frequently in stage IV BC." (PMID 32731384, 2020). "While 15 genes were found to be altered in two or more tumors, only 5 mutations occurred in more than one tumor model (ADCY2 p.V147L, ERBB2 p.I655V, NCF2 p.H308Q, SYNE1 p.L885V, and ZNF814 p.158V)." (PMID 26270481, 2015). "For example, genes such as SYNE1 and STARD3 were classified in the UV radiation response pathway, suggesting their relation to the hallmark of “Genome Instability and Mutation”, one of the pillars of tumor development." (PMID 40136626, 2025). "Dysregulation of SYNE1 or related proteins may therefore contribute to changes in the tumor microenvironment through indirect effects on gene expression program." (PMID 37671167, 2023). "The tumor burden mutations (TMB) correlation analysis showed that high TMB had a worse prognosis than low-TMB, and gene mutations were found to be different in high and low TMB groups, such as PIK3CA (36% versus 32%), SYNE1 (4% versus 6%)." (PMID 36203428, 2022). "In addition, a benign missense mutation in SYNE1 was identified in the tumor bed of another patient (No. 4)." (PMID 36428702, 2022). "In summary, we found two potential tumor antigens, ZNF831 and SYNE1, and identified four immune subtypes of HCC with distinct molecular features." (PMID 40948427, 2025).
tumor (continued). "Two potential tumor antigens, ZNF831 and SYNE1, showed significant superior prognostic effects and positive correlations with antigen presenting cells, which provided promising candidates for the development of tumor antigen‐based mRNA vaccine." (PMID 40948427, 2025). "Furthermore, two tumor antigens, ZNF831 and SYNE1, had positive correlations with antigen presenting cells." (PMID 40948427, 2025).
neurodegenerative disease (4 papers, 2015 to 2023). A disorder of the central nervous system characterized by gradual and progressive loss of neural tissue and neurologic function. "SYNE1, coding for nesprin-1, has recently been shown as neurodegenerative diseases causative gene." (PMID 28854936, 2017).
diseases of the nervous system (3 papers, 2012 to 2024). "Mutations in SYNE1 predominantly cause diseases of the nervous system." (PMID 36552829, 2022).
genetic disorder (3 papers, 2019 to 2024). "Although mutations in the human EMD gene are most closely tied to the genetic disorder EDMD1, similar phenotypes arise from mutations in genes coding for interacting proteins, such as LMNA, SYNE1, SYNE2, and TMEM43." (PMID 30871242, 2019).
myopathies (2 papers, 2014 to 2024). "Screening of SYNE1 (nesprin-1), SYNE2 (nesprin-2), and SUN1 and SUN2 genes identified variants in patients with EDMD or related myopathies." (PMID 38831796, 2024).
cardiac disease (1 paper, 2017). "Alternatively, in addition to these SYNE1 mutations, another cardiac disease gene is mutated thus enhancing the phenotype." (PMID 28398466, 2017).
hematologic malignancies (1 paper, 2025).
muscular disorders (1 paper, 2022). "Moreover, both SYNE1 and SYNE2 have been associated with muscular disorders." (PMID 36409768, 2022).
SYNE1 also shares sentences with these, for which no sentence is quoted: cerebellar ataxia (14 papers); autosomal recessive cerebellar ataxia (4); Duchenne muscular dystrophy (4); cervical cancer (3); oral cancer (3); spastic ataxia (3); adenocarcinoma (2); Alzheimer disease (2); Anxiety (2); Cerebellar atrophy (2); choriocarcinoma (2); congenital myopathies (2); diabetes (2); Friedreich ataxia (2); glioma (2); hepatocellular carcinoma (2); hypertriglyceridaemia (2); infection (2); Infertility (2); lung squamous cell carcinoma (2); pancreatic cancer (2); psychiatric disorder (2); squamous cell carcinoma (2); Arrhythmia (1); ataxia telangiectasia (1); autosomal recessive spinocerebellar ataxia 1 (1); axonal neuropathy (1); basal cell carcinoma (1); Becker muscular dystrophy (1); bladder cancer (1).
A further 53 diseases each share a sentence with SYNE1 in 1 paper.